MT-TD (mitochondrially encoded tRNA-Asp (GAU/C))
Synonyms: trnD; formerly MTTD
Gene: Mitochondrial transfer RNA gene on chromosome MT (7,518 to 7,585, forward strand). Ensembl gene ENSG00000210154.
Gene-disease validity (ClinGen):
ClinGen rates the evidence that MT-TD causes each of these diseases.
mitochondrial disease (mitochondrial): Moderate.